SQLE (squalene epoxidase)
Description:
Catalyzes the stereospecific oxidation of squalene to (S)-2,3-epoxysqualene, and is considered to be a rate-limiting enzyme in steroid biosynthesis.
Tractability: Small molecule: a structure with a bound ligand is known; it belongs to a druggable protein family. Antibody: UniProt places it where antibodies can reach, with high confidence. PROTAC: UniProt records ubiquitination sites on it; ubiquitination databases record sites on it; its protein half-life has been measured; a small molecule that binds it is known.
Target class: Enzyme; Oxidoreductase
Gene: Protein-coding gene on chromosome 8 (124,998,467 to 125,022,287, forward strand). Ensembl gene ENSG00000104549.
Subcellular location: Microsome membrane; Endoplasmic reticulum membrane
Subcellular location (Human Protein Atlas): Cytosol; Vesicles
Pathways (Reactome):
Metabolism: Activation of gene expression by SREBF (SREBP); Lanosterol biosynthesis
Gene Ontology:
Molecular function: FAD binding; protein binding; squalene monooxygenase activity; flavin adenine dinucleotide binding
Biological process: cholesterol biosynthetic process; lipid droplet formation; regulation of cell population proliferation; sterol biosynthetic process; cholesterol metabolic process; response to biphenyl; zymosterol biosynthetic process
Cellular component: endoplasmic reticulum membrane; intracellular membrane-bounded organelle; membrane; endoplasmic reticulum; cytoplasmic side of endoplasmic reticulum membrane
Genetic constraint (gnomAD): Loss-of-function variants: 21 observed, 48.09 expected, observed/expected ratio (o/e) 0.44, 90% interval 0.31 to 0.63. The upper end of that interval is the gene's LOEUF score, 0.63, which puts it in group 2 of 6, group 1 being the genes least tolerant of losing a copy. Missense variants: 546 observed, 611.02 expected, observed/expected ratio (o/e) 0.89, 90% interval 0.83 to 0.96. Synonymous variants: 214 observed, 222.99 expected, observed/expected ratio (o/e) 0.96, 90% interval 0.86 to 1.08.
Homologues: Orthologues: chimpanzee SQLE (99% identical), macaque SQLE (97% identical), rabbit SQLE (90% identical), dog SQLE (87% identical), pig SQLE (86% identical), mouse Sqle (84% identical), rat Sqle (84% identical), guinea pig SQLE (81% identical), tropical clawed frog sqle (66% identical), zebrafish sqlea (63% identical), zebrafish sqleb (52% identical).
Diseases named in the same sentence as SQLE in open-access papers:
SQLE is named in the same sentence as 71 diseases in open-access papers, as found by Europe PMC text mining. Sharing a sentence is not in itself a finding about the gene and the disease. The quoted sentences say what the papers report.
breast carcinoma (25 papers, 2007 to 2025). "In breast cancer, SQLE overexpression is usually associated with tumor aggressiveness, recurrence, and overall survival time, and breast cancers with amplification of 8q24.11–13 (a region that includes the SQLE gene) imply a poorer prognosis." (PMID 39588004, 2024). "Previous studies revealed that, as a ferroptosis regulator, SQLE was associated with the proliferation and metastasis of breast cancer." (PMID 35962621, 2022). "Meanwhile, SQLE, which encodes squalene epoxidase a rate-limiting enzyme in sterol biosynthesis and a significant therapeutic target for breast cancer, was upregulated in EOBC tumor tissue." (PMID 33807872, 2021). "We identified mRNA expression of SQLE, located on chromosome 8q24.1, to be associated with high-risk ER+ breast cancer cases." (PMID 18728668, 2008). "Squalene epoxidase mRNA expression was able to define a patient subgroup at significantly increased risk of early onset of metastasis among ER+ stage I/II breast cancer." (PMID 18728668, 2008). "Of the genes that were differentially expressed by race, high expression of one gene, SQLE, was also associated with an increased risk of breast cancer recurrence and thus may be a potential disparity-associated gene." (PMID 29228969, 2017). "A recognized oncogenic gene in breast cancer, SQLE is a crucial enzyme in the production of cholesterol." (PMID 38622617, 2024). "SQLE is a key rate-limiting enzyme in cholesterol biosynthesis that has been demonstrated as a bona fide oncogene in liver and breast cancer." (PMID 39349433, 2024). "CASIMO1 is a micropeptide that localizes to endosomes and interacts with squalene epoxidase (SQLE) to influence cell proliferation and cycle progression and regulates lipid droplet accumulation in breast cancer cells." (PMID 38622617, 2024). "SQLE is a key enzyme of cholesterol biosynthesis and tends to be over-expressed along with treatment sensitivity in colon cancer, breast cancer and non-small cell lung cancer, Acute Myeloid Leukemia and pancreatic cancer." (PMID 36536343, 2022). "As a ferroptosis regulator, SQLE was identified as a crucial cancer‐promoting gene in the breast cancer." (PMID 35962621, 2022). "An abnormal expression of the SQLE gene in abnormal cholesterol metabolism cells has been reported, such as prostate cancer, breast cancer, and lung cancer." (PMID 32120850, 2020). "Previously reported race and survival-associated genes including MUC1, GSTT2, PSPHL, SQLE, and TYMS were associated with race in this population-based study of women diagnosed with breast cancer." (PMID 29228969, 2017). "These subtype-specific breast cancer metabolism signatures contained a common set of five genes (SQLE, PYCRL, TSTA3, CYC1 and SLC39A4) which were co-amplified with MYC on chromosome 8q24 and showed a positive correlation with hypoxia." (PMID 27358048, 2016). "We therefore quantified mRNA levels for HMGCR and SQLE in an ERα breast cancer patient treated with AI for whom we had longitudinal data (RNA obtained at diagnosis, first relapse and in circulating metastatic cells from pleural effusion)." (PMID 26610607, 2015). "mRNA expression of the key enzyme of cholesterol biosynthesis, squalene epoxidase (SQLE, chromosomal location 8q24.1), was associated with ER+ 7p+/8q+ breast cancer." (PMID 18728668, 2008). "Moreover, SQLE is a race- and survival-related gene in breast cancers that is more highly expressed in African women compared to their Caucasian counterparts and indicates poor survival." (PMID 38612682, 2024). "SQLE, the second rate-limiting enzyme in the cholesterol biosynthesis, was found to be elevated in several cancers such as hepatocellular carcinoma, breast cancer, head and neck squamous cell carcinoma, and prostate cancer, contributing to tumor progression and poorer outcomes for patients." (PMID 37542052, 2023).
breast carcinoma (continued). "Recently, SQLE upregulation was reported and identified as a prognostic marker in a variety of disease, such as non-alcoholic steatohepatitis 26, hepatocellular carcinoma 27 and breast cancer." (PMID 35813482, 2022). "Interestingly, SQLE has been identified as an oncogene in breast cancer cells, suggesting it plays a role in breast cancer metabolism." (PMID 34141606, 2021). "Specifically, we sought to estimate differences in the expression of two suspected good prognosis genes (ACOX2 and MUC1) and six suspected poor prognosis genes (FAM177A1, GSTT2, PSPH, PSPHL, SQLE, and TYMS) by race, and to examine their associations with risk of breast cancer recurrence." (PMID 29228969, 2017). "Six of the 11 non-mitosis related genes were previously associated with poor survival in breast cancer patients: KRT17, MMP12, SLC7A5, SQLE, GABRP and PA2G4, but the remaining 5 had not been previously associated with cancer risk: CCDC86, NUP107, NUTF2, WASF1 and ELOVL6." (PMID 23077491, 2012). "Core metabolic prognostic signatures are identified, comprising NUDT1 and GAPDH in kidney renal cell carcinoma and SQLE, ALG3 and PSPH in two independent breast carcinoma cohorts." (PMID 27358048, 2016). "A previous study has revealed that lncRNA 030 maintains the stemness of breast cancer stem cells by interacting with PCBP2, regulating the stability of squalene monooxygenase (SQLE) mRNA, promoting cellular cholesterol synthesis, and further leading to activation of the PI3K/AKT pathway." (PMID 38238756, 2024). "It interacts with the key enzyme of cholesterol synthesis, squalene epoxidase (SQLE), to regulate the metabolic homeostasis of cancer cells, thereby influencing cell proliferation and cell cycle progression, and regulating lipid droplet accumulation in breast cancer cells." (PMID 40264667, 2025).
hepatocellular carcinoma (13 papers, 2018 to 2025). A malignant tumor that arises from hepatocytes. "Indeed, perturbed expression of key cholesterol biosynthesis enzymes, such as HMGCR and SQLE, prevents carcinogenesis in colorectal cancer, breast cancer, prostate cancer and hepatocellular carcinoma associated with nonalcoholic fatty liver disease (NAFLD-HCC)." (PMID 32712598, 2020). "Squalene epoxidase (SQLE) is known to promote the growth and migration of hepatocellular carcinoma cells." (PMID 39684755, 2024). "Reports indicate high expression of squalene monooxygenase (SQLE) in breast and hepatocellular carcinoma and plays a key role in induction of epithelial-mesenchymal transition in esophageal carcinoma." (PMID 29728663, 2018). "Similarly, SQLE is upregulated in nasopharyngeal cancer, head and neck squamous cell carcinoma, leukemia, hepatocellular cancer, and squamous lung cancer." (PMID 36091156, 2022). "In summary, the highly conserved gga-miR-221-5p was proved to directly target ELOVL6 and SQLE mRNAs to affect the level of intracellular triglyceride and total cholesterol in LMH chicken hepatoma cells." (PMID 32120850, 2020). "Although SQLE has been shown as an oncogene that is overexpressed in several cancers, including hepatocellular carcinoma (HCC) and colorectal cancer (COAD), and overexpression of SQLE tends to bring a bad prognosis in these cancers, the interaction between BCa and SQLE remains poorly understood." (PMID 37770925, 2023).
colorectal cancer (9 papers, 2016 to 2024). A primary or metastatic malignant neoplasm that affects the colon or rectum. "Further validation in breast and colorectal cancer cell lines highlighted squalene epoxidase, an oxygen-requiring enzyme in cholesterol biosynthesis, as a driver of dysregulated metabolism and a key player in maintaining cell survival under hypoxia." (PMID 27358048, 2016). "Thus, the SQLE gene may act as an oncogene, but whether it plays a role in colorectal cancer remains unknown." (PMID 31072053, 2019).
dermatophytosis (8 papers, 2022 to 2026). A common fungal infection of the stratum corneum of the skin, hair, or nails by a dermatophyte. "In refractory dermatophytosis, terbinafine resistance has been attributed to a point mutation in the squalene epoxidase gene." (PMID 38276250, 2023). "Extensive dermatophytosis caused by terbinafine-resistant Trichophyton indotineae harboring Phe397Leu and Leu393Ser substitutions in the squalene epoxidase enzyme was diagnosed in France." (PMID 34932456, 2022). "We performed a one-year multicentre, hospital-based survey of referred cases (September 2023-September 2024) in nine provinces of Iran to describe the current epidemiology of dermatophytosis and to analyse mutations in the squalene epoxidase (SQLE) gene associated with terbinafine (TRB) resistance." (PMID 41769351, 2026). "Terbinafine, a first-line treatment for dermatophytosis, acts by inhibiting the enzyme squalene epoxidase." (PMID 38276250, 2023). "Systemic antifungals, such as terbinafine, a first-line oral antifungal that inhibits the enzyme squalene epoxidase (SQLE), are used to treat refractory or extensive dermatophytosis or infections involving hair follicles or nails." (PMID 38748419, 2024).
fungal infections (8 papers, 2017 to 2024). "Rapid discrimination of MDR strains from sensitive ones consists of a growth test using fungicides that are not used in agriculture, such as tolnaftate and terbinafine, both squalene epoxidase inhibitors typically used against human fungal infections." (PMID 29085913, 2017). "SQLE inhibition is targeted for the treatment of hypercholesteremia, cancer, and fungal infections." (PMID 30626872, 2019). "With potent and selective inhibition of squalene epoxidase, broad antifungal activity, significant accumulation in skin layers, and direct impact on fungal cell membranes, allylamines and benzylamines remain agents of choice for several fungal infections of the skin." (PMID 36557078, 2022). "SQLE inhibitors, such as terbinafine, NB598, natural compounds, and their derivatives, can effectively ameliorate fungal infections, nonalcoholic fatty liver disease, and cancer." (PMID 39588004, 2024). "Squalene epoxidase (SQLE) is an essential enzyme for cholesterol biosynthesis, and a clinical target for treatment of hypercholesteremia, cancer, and fungal infections." (PMID 34639020, 2021).
prostate carcinoma (8 papers, 2018 to 2025). A carcinoma that arises from epithelial cells of the prostate gland. "In a study on prostate cancer, it was found that PTEN loss promotes the transcription of the SQLE gene by activating SREBP-2, thereby upregulating the expression of squalene epoxidase (SQLE)." (PMID 40426972, 2025). "We have recently shown that squalene epoxidase (SQLE) is upregulated in aggressive prostate cancer through a micro-RNA dependent mechanism to drive de novo cholesterol biosynthesis." (PMID 37202505, 2023). "This notion was also in line with a recent study showing increased activity of the cholesterol synthesis enzyme squalene monooxygenase (SQLE) in lethal prostate cancer." (PMID 29703166, 2018).
head and neck squamous cell carcinoma (7 papers, 2022 to 2024). A squamous cell carcinoma that arises from any of the following anatomic sites: lip and oral cavity, nasal cavity, paranasal sinuses, pharynx, larynx, and salivary glands. "SQLE overexpression is also associated with worse survival in uveal melanoma, nasopharyngeal carcinoma, and head and neck squamous cell carcinoma." (PMID 36091156, 2022). "Recently, it was reported that the lower expression of miR-584-5p in head and neck squamous cell carcinoma (HNSCC) compared to paratumor oral mucosa is responsible for the upregulation of SQLE, an enzyme involved in cholesterol synthesis." (PMID 39000555, 2024). "This study delineates the crucial role of squalene epoxidase (SQLE) in driving chemoresistance and tumorigenesis in head and neck squamous cell carcinoma." (PMID 37490552, 2023). "Further, by enhancing de novo cholesterol biosynthesis, squalene epoxidase (SQLE) promoted the activation of downstream PI3K/Akt and induced cisplatin resistance in head and neck squamous cell carcinoma (HNSCC)." (PMID 39624081, 2024).
pancreatic cancer (7 papers, 2021 to 2025). "This study marks a significant advancement in identifying potent squalene epoxidase (SQLE) inhibitors for pancreatic cancer treatment." (PMID 39654652, 2024). "LncRNA‐TTN‐AS1 functioned as a sponge of miR‐133b to upregulate the expression of SQLE, thereby promoting the development of pancreatic cancer." (PMID 35638462, 2022). "SQLE, a key enzyme for lipid precursor synthesis in ferroptosis, can stimulate the malignant capabilities of pancreatic cancer cells." (PMID 34761566, 2021). "Among 39 differentially expressed factors, seven up-regulated genes (CAV2, CIDEC, HILPDA, HSD17B11, NCEH1, RAB5A, and SQLE) and two down-regulation genes (BSCL2 and FITM1) were significantly associated with overall survival of pancreatic cancer patients." (PMID 34078402, 2021). "Given that SQLE is overexpressed in pancreatic cancer and plays a role in tumor progression through cholesterol metabolism, targeting this enzyme with HCJ007 could lead to reduced tumor growth and improved patient outcomes." (PMID 39654652, 2024). "We further identified that enhanced expression of 7 genes namely CAV2, CIDEC, HILPDA, HSD17B11, NCEH1, RAB5A, and SQLE are associated with significantly shorter overall survival whereas elevated expression of BSCL2 and FITM1 correlates with longer overall survival of pancreatic cancer patients." (PMID 34078402, 2021). "Leveraging the diverse chemical landscape of marine-derived compounds, this study has identified promising squalene epoxidase (SQLE) inhibitors, advancing the search for effective pancreatic cancer treatments." (PMID 39654652, 2024). "SQLE’s mechanistic action is twofold: it alleviates endoplasmic reticulum stress and activates the lipid raft-mediated Src/PI3K/Akt signaling pathway, thus propelling pancreatic cancer growth." (PMID 39654652, 2024). "Therefore, we speculated that lncRNA‐TTN‐AS1 could regulate the expression level of SQLE by sponging miR‐133b, and then acted on the ERK/NF‐κB pathway to affect the progression of pancreatic cancer." (PMID 35638462, 2022).
anaplastic large cell lymphoma (3 papers, 2021). Anaplastic large cell lymphoma (ALCL) is a rare and aggressive peripheral T-cell non-Hodgkin lymphoma, belonging to the group of CD30-positive lymphoproliferative disorders, which affects lymph nodes and extranodal sites. "When squalene epoxidase is inactivated, an excess of squalene altered the cellular lipid profile and protected anaplastic large cell lymphoma from ferroptotic cell death, providing a growth advantage of tumors under oxidative stress." (PMID 34440098, 2021). "Some tumors, such as ALK+ anaplastic large cell lymphoma (ALCL), lose the expression of SQLE, which mediates the generation of cholesterol from squalene, indicating that these tumors are dependent on exogenous cholesterols." (PMID 33801564, 2021).
cervical cancer (3 papers, 2022 to 2026). A primary or metastatic malignant neoplasm involving the cervix. "In the study, APOD, APOC1 and SQLE were identified as prognostic genes, and a prognostic genes-based risk model was constructed and validated, which will provide a novel viewpoint and reference value for the treatment and prognosis of cervical cancer." (PMID 36536343, 2022). "The genes SQLE, APOC1, H1.2, GCH1, and EEF1A1 were determined to be associated with cervical cancer." (PMID 41583517, 2026). "Simultaneously, the mRNA expression of APOD, APOC1, and SQLE was further assayed in cervical cancer tissues and normal tissues." (PMID 36536343, 2022). "After one-way and multivariate analysis of variance, we finally obtained three prognostic genes of APOD, APOC1 and SQLE significantly related to survival, and the expression of which was assayed in 10 cervical cancer tissue samples and 10 normal samples by RT-qPCR." (PMID 36536343, 2022). "A previous research group established a 4-gene signature related to ferroptosis of cervical cancer patients (TFRC, ACACA, SQLE and PHKG2)." (PMID 36313765, 2022).